PIAS4 (protein inhibitor of activated STAT 4)
Description:
Functions as an E3-type small ubiquitin-like modifier (SUMO) ligase, stabilizing the interaction between UBE2I and the substrate, and as a SUMO-tethering factor. Mediates sumoylation of ALKBH5, AXIN1, CEBPA, KLF8, GATA2, PARK7, HERC2, MYB, TCF4 and RNF168. Involved in gene silencing. In Wnt signaling, represses LEF1 and enhances TCF4 transcriptional activities through promoting their sumoylations. Enhances the sumoylation of MTA1 and may participate in its paralog-selective sumoylation. Binds to AT-rich DNA sequences, known as matrix or scaffold attachment regions (MARs/SARs) (By similarity). Catalyzes conjugation of SUMO2 to KAT5 in response to DNA damage, facilitating repair of DNA double-strand breaks (DSBs) via homologous recombination (HR). Mediates sumoylation of PARP1 in response to PARP1 trapping to chromatin. Mediates sumoylation of KLF8, repressing KLF8 transcriptional activity and cell cycle progression into G(1) phase. Sumoylates ALKBH5 downstream of MAPK8/JNK1 and MAPK9/JNK2 in response to reactive oxygen species (ROS), inhibiting ALKBH5 RNA demethylase activity.
Synonyms: PIAS-gamma; PIASG; PIASY; FLJ12419; ZMIZ6
Tractability: PROTAC: UniProt records ubiquitination sites on it; ubiquitination databases record sites on it; its protein half-life has been measured.
Target class: Enzyme; Transferase
Gene: Protein-coding gene on chromosome 19 (4,007,695 to 4,039,386, forward strand). Ensembl gene ENSG00000105229.
Subcellular location: Nucleus, PML body
Subcellular location (Human Protein Atlas): Nucleoplasm; Centrosome
Pathways (Reactome):
Metabolism of proteins: SUMOylation of DNA damage response and repair proteins; SUMOylation of DNA replication proteins; SUMOylation of SUMOylation proteins; SUMOylation of immune response proteins; SUMOylation of intracellular receptors; SUMOylation of transcription cofactors; SUMOylation of transcription factors; SUMOylation of ubiquitinylation proteins
DNA Repair: Nonhomologous End-Joining (NHEJ); Processing of DNA double-strand break ends; Recruitment and ATM-mediated phosphorylation of repair and signaling proteins at DNA double strand breaks
Cell Cycle: G2/M DNA damage checkpoint
Metabolism: Vitamin D (calciferol) metabolism
Gene Ontology:
Molecular function: protein binding; SUMO ligase activity; SUMO transferase activity; ubiquitin protein ligase activity; ubiquitin protein ligase binding; transcription coregulator activity; transcription regulator inhibitor activity; zinc ion binding; DNA binding; transcription corepressor activity
Biological process: negative regulation of DNA-templated transcription; negative regulation of protein localization to chromatin; positive regulation of double-strand break repair via homologous recombination; positive regulation of protein sumoylation; protein sumoylation; regulation of mRNA stability; double-strand break repair; negative regulation of receptor signaling pathway via JAK-STAT; positive regulation of keratinocyte apoptotic process; regulation of transcription by RNA polymerase II; vitamin D metabolic process; negative regulation of canonical NF-kappaB signal transduction; regulation of cellular response to stress; regulation of gene expression
Cellular component: cytoplasm; nucleoplasm; nucleus; chromatin; nuclear matrix; PML body; transferase complex
Genetic constraint (gnomAD): Loss-of-function variants: 7 observed, 52.87 expected, observed/expected ratio (o/e) 0.13, 90% interval 0.074 to 0.25. The upper end of that interval is the gene's LOEUF score, 0.25, which puts it in group 1 of 6, group 1 being the genes least tolerant of losing a copy. Missense variants: 550 observed, 700.78 expected, observed/expected ratio (o/e) 0.78, 90% interval 0.73 to 0.84. Synonymous variants: 364 observed, 310.31 expected, observed/expected ratio (o/e) 1.17, 90% interval 1.08 to 1.28.
Homologues: Orthologues: chimpanzee PIAS4 (99% identical), macaque PIAS4 (98% identical), pig PIAS4 (95% identical), dog PIAS4 (95% identical), guinea pig PIAS4 (93% identical), mouse Pias4 (89% identical), rat Pias4 (89% identical), tropical clawed frog pias4 (79% identical), zebrafish pias4a (59% identical), zebrafish pias4b (40% identical), Drosophila melanogaster Su(var)2-10 (38% identical). Paralogues in human: PIAS1 (47% identical), PIAS2 (47% identical), PIAS3 (46% identical), ZMIZ2 (24% identical), ZMIZ1 (23% identical).